FABP4 (fatty acid binding protein 4)
Diseases named in the same sentence as FABP4 in open-access papers (continued):
Sharing a sentence is not in itself a finding about the gene and the disease.
Obesity (continued). "In animal models of obesity and insulin resistance it was shown that the inhibition of FABP4 protein in macrophages reduces inflammatory cytokines (MCP-1, IL-1β, IL-6 and TNFα) and the formation of atherosclerotic lesions and foam cells and improves insulin sensitivity." (PMID 34834808, 2021). "In recent studies, adiponectin and fatty acid binding protein 4 (FABP4) were usually considered as the specific markers of EVs from adipocytes, while perilipin A was identified as a biomarker of stressed adipocytes in case of obesity in both human and mice." (PMID 34108967, 2021). "RBP4 and FABP4 could be considered as detrimental to metabolism because they exhibit high circulating levels and adipose tissue gene expression with obesity related disorders." (PMID 34638803, 2021). "It was reported that circTshz2-2 increases adipogenesis-related gene expression, such as Pparγ and Fabp4, in obesity while other reports suggest that Tshz2 regulates tumorigenesis and epigenetic methylation in breast and prostate cancers, and is involved in the development of zebrafish." (PMID 34561612, 2021). "In conclusion, obesity-associated immunometabolic factors including LDL-cholesterol, FABP4, and leptin were associated with a higher iNKT cell IFN-γ response across all disease groups, while HDL-cholesterol and insulin sensitivity (QUICKI) were associated with a higher IL-4 response." (PMID 34635725, 2021). "FABP4 and FABP2 have recently been reported to have a significant association with cancer progression in patients with colorectal cancer and several studies demonstrate that obesity and high fat intake are risk factors in colorectal cancer." (PMID 32209538, 2020). "The results were similar to those of in vitro studies showing that combined administration of CO and RF in HFD-induced obese mice promoted the downregulation of adipogenesis-associated genes Cebpa, Fabp4, Pparg and Srebp1 compared to those in HFD-induced-obesity mice." (PMID 32443487, 2020). "Since also macrophages release FABP4, although at lower levels than adipocytes, these cells may contribute to increase the serum level of FABP4 in obesity." (PMID 32856199, 2020). "Furthermore, the knockout of FABP4 decreases oxidative stress and uncouples obesity from inflammation in macrophages." (PMID 31996081, 2020). "In human obesity studies FABP4 expression was down-regulated in AT, which may explain excessive fat uptake by other tissues such as the liver." (PMID 32321549, 2020). "Circulating FABP4 levels are increased in obesity and metabolic diseases in humans and rats." (PMID 32321549, 2020). "Similarly, FABP4 is believed to play an important role in the prostatic cancer stroma and influence PCa metastasis/progression, especially under obesity and/or high-fat diet conditions." (PMID 33352874, 2020). "There were significant correlations between body weight gain, adipose tissue weight, and adipocyte expression of Fabp4, Fasn, Wfdc21, and Hp, indicating that the observed anti-obesity effect is mediated via the modulation of fatty acid synthesis and inflammation in adipose tissues." (PMID 32824369, 2020). "Secreted FABP4 can also stimulate the prostate stroma cells to produce cytokines such as IL-6 and IL-8, which in turn drive PCa invasion and metastasis, especially under high-fat diets and obesity." (PMID 33352874, 2020). "In addition, Hao and collaborators showed that circulating adipose tissue-derived fatty acid binding protein 4 (FABP4) levels increase during obesity and can activate the axis IL-6/STAT3/ALDH1, thus driving cancer stemness." (PMID 33371274, 2020). "However, decreased responsiveness for diet-induced obesity has been a repeated finding in Fabp4-Cre mice." (PMID 32610701, 2020). "Studies have shown that knocking out the FABP4 gene in mouse adipocytes can reduce the expression of inflammatory factors in macrophages and the inflammatory response in adipose tissue, which can lead to obesity." (PMID 31651326, 2019).
Obesity (continued). "In addition to the increased FABP4 circulating levels observed in experimental models of obesity, a positive correlation between FABP4 levels, obesity and type 2 diabetes has been reported in several cohorts of patients." (PMID 30575815, 2019). "However, in obesity, where there is abundant adipose tissue, insulin resistance, and uncontrolled lipolysis, FABP4 is constantly engaged." (PMID 30705117, 2019). "Transgenic (Tg) mouse models overexpressing PHB (PHB-Tg) and a phospho-mutant PHB (mPHB-Tg) from the fatty acid binding protein-4 (Fabp-4) gene promoter display sex-neutral obesity; however, obesity-related insulin resistance and metabolic dysregulation are male-specific." (PMID 31118075, 2019). "Mechanisms of FABP4 secretion from adipose tissue have been strongly correlated with signals downstream of lipolytic stimuli, which are consistently engaged during insulin resistance, stress, and obesity." (PMID 30705117, 2019). "Suppression of PPARγ by FABP4 in visceral fat may explain the reported role of FABP4 in the development of obesity-related morbidities, including insulin resistance, diabetes, and atherosclerosis." (PMID 30857223, 2019). "An involvement of FABP4 in the pathogenesis of obesity and insulin resistance might be mediated via FABP4-dependent PPARγ inhibition." (PMID 30857223, 2019). "However, chronic engagement of FABP4 under conditions of immunometabolic stress, such as obesity, exacerbates a number of immunometabolic diseases, including diabetes, asthma, cancer, and atherosclerosis." (PMID 30705117, 2019). "Last, we could not measure other obesity-associated adipokines such as other obesity-associated adipocytokines such as TNFα, leptin, IL6, IL8, MCP1, and FABP4 because of the limited quantity of samples." (PMID 32117043, 2019). "FABP4 may act as a mediator between diabetes and obesity due to its role in lipid metabolism and glucose utilization." (PMID 30670722, 2019). "Importantly, most of the disease correlations with serum FABP4 levels are observed in the context of obesity, suggesting that adipocyte-derived FABP4 is likely to be the source of this pathogenic molecule." (PMID 30705117, 2019). "FABP4 is expressed in adipose tissue, and is related to obesity and diabetes mellitus." (PMID 30453990, 2018). "Clinically, the serum level of FABP4 was significantly associated with an aggressive type of PCa rather than obesity." (PMID 29340091, 2017). "Moreover, a clinical study has suggested an antagonistic effect of Irisin on fatty acid binding protein 4 (FABP4), the FA binding protein, which is associated with an increased risk of obesity-related metabolic disorders and HTN." (PMID 28750629, 2017). "Studies have shown that blocking the expression of fatty acid-binding protein (FABP4/AP2) could improve inflammation-induced obesity by modulating the upregulated expression of uncoupling protein 2 (UCP2)." (PMID 28770376, 2017). "The action of FABP4 in obesity may occur clinically, but further studies are needed to verify this point." (PMID 28654680, 2017). "FABP4 may have an important role in the restive prostatic stroma and influence PCa progression, especially under obesity and/or HFD conditions." (PMID 29340091, 2017). "Among FABPs, fatty acid-binding protein 4 (FABP4), also referred to as adipocyte FABP (A-FABP) or aP2, is mainly expressed in both adipocytes and macrophages and plays an important role in the development of obesity, insulin resistance, type 2 diabetes mellitus and atherosclerosis." (PMID 27124282, 2016). "Given that obesity influences the levels of FABP4, our small sample size cannot conclude whether obesity contributes to the results." (PMID 26823558, 2016). "Secreted by fat tissue, the cytokine FABP4 plays a key role in obesity." (PMID 26752184, 2016). "Exogenous FABP4 also have many important functions in obesity and atherogenesis." (PMID 27294862, 2016).
Obesity (continued). "Elevated FABP4 levels increase the risks of obesity-related metabolic disorders and hypertension." (PMID 26752184, 2016). "However, we found that Fabp4-Cre-induced deletion of Bdnf or Ntrk2 led to hyperphagia, obesity, and aggressiveness, presumably due to ectopic Fabp4-Cre mediated gene recombination in the brain." (PMID 28721258, 2015). "Serum levels of FABP4 are elevated in obesity and metabolic syndrome and may contribute to development of nonalcoholic steatohepatitis (NASH)." (PMID 24205333, 2013). "We and other authors have shown that FABP4 levels are increased in obesity, metabolic syndrome (MS), type 2 diabetes (T2D), and familial combined hyperlipidaemia or lipodystrophy syndromes, and these levels are also closely correlated with adverse lipid profiles and insulin resistance." (PMID 22709426, 2012). "We hypothesized that FABP4 may have an important role in the metabolic balance of the adipose and liver tissue in obesity." (PMID 23139800, 2012). "A recent study has shown that FABP4 levels could be a novel and obesity-independent prognostic factor in patients with breast cancer." (PMID 22121495, 2011). "Moreover, adipose fatty acid binding protein 4 (FABP4) which is also elevated in obesity has a significant positive correlation with TG-rich VLDL and inverse correlation with HDL-C." (PMID 21988829, 2011). "The release of leptin and FABP-4 by fat cells is also enhanced in human obesity." (PMID 20508843, 2010). "Adipocyte FABP, also known as FABP4, A-FABP, or aP2, was initially detected in mature adipocytes, and plays critical roles in hyperlipidemia, atherogenesis and type 2 diabetes, particularly when obesity is concurrently present)." (PMID 20156355, 2010). "The purpose of this study was to measure FABP4 plasma levels, assess FABP4 allelic variants, and explore potential associations with fasting glucose and insulin levels in young school-age children with and without obesity." (PMID 20156355, 2010). "Thus, findings in this study suggest that FABP‐4, as an obesity‐related biomarker, may be a mediator in the BMI‐mortality relationship in persons with CRC." (PMID 40857027, 2026). "Moreover, FABP‐4, a protein involved in metabolic regulation and inflammation that has been found to be elevated in obesity, could partially explain the body mass index–mortality association in individuals with colorectal cancer." (PMID 40857027, 2026). "Therefore, FABP‐4 may be relevant for the prognosis of CRC patients and could qualify as a potential biomarker linking obesity and risk of mortality in individuals who are diagnosed with CRC." (PMID 40857027, 2026). "Additionally, studies have documented the effect of moringa on adipogenesis by regulating C/EBPα, adiponectin, FABP4, and PPARγ, as well as augmenting thermogenesis in adipose tissue, which testifies to the anti-obesity effect of moringa and supports the current findings." (PMID 41011207, 2025). "In the context of obesity, we anticipate that the elevated levels of circulating FABP4, combined with increased lipid content in adipocytes, uncontrolled lipolysis, and ectopic lipid deposition in other organs, may collectively contribute to the heightened disease severity." (PMID 39843629, 2025). "In addition, the serum FABP4 level of obese mice increases significantly, suggesting that obesity may further enhance the role of FABP4 in promoting the release of pro-inflammatory molecules such as TNFα and IL-6." (PMID 38456906, 2024). "Moreover, FABP4 inhibitors have also been proposed as potential therapies for lipid disorders, particularly high triglycerides, acute kidney injury, obesity-related cancer, obesity, and diabetes." (PMID 38731797, 2024). "Importantly, human obesity is also characterized by an increase in sympathetic tone, which may also contribute to the observed correlation between hormonal FABP4 and BMI, and exacerbate the pathological elevations of circulating FABP4." (PMID 37172691, 2023).
Obesity (continued). "However, FABP4 is robustly upregulated in an obese mouse model and obesity-promoted HCC model." (PMID 36060264, 2022). "As a result, consumption of kefir containing Lactobacillus kefiri DH5 upregulates the expression of CPT1 and FABP4 genes, thereby can increase β-oxidation of fatty acids and lipolysis and can decrease lipogenesis in metabolism and may have an anti-obesity effect." (PMID 34945650, 2021). "Furthermore, FABP4 serum and adipose tissue level could be modulated by obesity; hence, we analyzed patients with central obesity and potential metabolic complications separately from non-obese patients." (PMID 34609443, 2021). "Indeed, Fabp4−/− mice are protected from obesity-induced insulin resistance and hyperglycemia." (PMID 30575815, 2019). "Therefore, promoter methylation was investigated at these loci, as well as at previously identified gene promoters reported in the literature to be regulated by DNA methylation in response to high-fat diet, obesity or T2D (Leptin, Pparg, Glut4, Fasn, Irs1, Hmox1, Fabp4)." (PMID 30728429, 2019). "The improvement of obesity might reduce the secretion of FABP4 by adipocytes." (PMID 26752184, 2016). "However, the adipocyte fatty acid binding protein (FABP4, also known as A-FABP and aP2), which is secreted from adipocytes and macrophages, has recently been investigated as a marker that is closely associated with obesity and metabolic syndrome." (PMID 26752184, 2016). "Notably, down-regulation of FABP4 expression and inhibition of lipolysis through AMPK activation and/or PKA inactivation in adipocytes may be involved in the improvement of obesity-associated glucose tolerance by DDT." (PMID 22428043, 2012). "More recently, targeted deletion of certain FABPs in murine models has revealed that FABP4 and FABP5 deficient mice are protected against diet-induced obesity, insulin resistance, type 2 diabetes, and a fatty liver, implying that these proteins may play a role in regulating liver fat." (PMID 23139800, 2012). "In particular, both FABP4 and FABP5 have emerged as key contributors to obesity-induced IR: their dual silencing in white adipose tissue significantly reduced inflammation and improved insulin sensitivity in preclinical models." (PMID 41372973, 2025). "In vivo experiments suggested that obesity resulted in the increase of the ratio of Emcn‐positive cells within IVD tissue, whereas knocking out FABP4 ameliorated this pathological alternation." (PMID 40090836, 2025). "Firstly, we detected expression levels of key adipogenesis genes, such as CEBPA, PPARG, lipoprotein lipase (LPL), fatty acid binding protein 4(FABP4) and perilipin 1 (PLIN1), which play critical roles in the development of obesity." (PMID 39773638, 2025). "Collectively, this present study demonstrated a new regulation axis, FABP4/AGEs‐RAGE signalling axis to activate NFκB signalling pathway, which will facilitate a better understanding of the pathological mechanism between obesity and IVDD." (PMID 40090836, 2025). "This enhanced understanding of the metabolic interplay among obesity, the TME, and cancer survival underscores the potential of targeting metabolic modulators such as FABP4 in the management of drug-resistant CRC." (PMID 39823981, 2025). "Here, we elucidate the molecular mechanisms by which adipocyte OGT promotes the differentiation of HSCs into monocytes in obesity, regulating monocyte formation through the OGT-NEFA-CD36/FABP4 pathway." (PMID 40389445, 2025). "Collectively, these experiments above demonstrated that FABP4 was the critical regulator for obesity‐induced IVDD, and inhibiting the expression of FABP4 showed favorable effects on obesity‐related IVDD." (PMID 40090836, 2025). "Despite these well‐documented roles of FABP4 in metabolic and inflammatory diseases, its involvement in IVDD, particularly in the context of obesity, remains poorly understood." (PMID 40090836, 2025).
Obesity (continued). "This analysis showed that some proteins, such as COL1A1, COL6A3, FABP4, LEP, LGALS1, and THBS4, are obesity-specific, and GDF15, LPL, MCFD2, REG1A, REG1B, and TCN2 are T2D-specific." (PMID 38732002, 2024). "In murine models, selective overexpression of WNT10B from the fatty-acid binding protein 4 (FABP4) promoter repressed the expression of the adipogenic program in adipocytes, thus impairing adipose tissue development and preventing obesity in mice." (PMID 38788527, 2024). "With high statistical significance, proteins FABP4, FCN2, and LEP showed 2-fold, 2.6-fold, and 4-fold increases in expression in the group of individuals with obesity, respectively." (PMID 38732002, 2024). "As most research on FABP4 and CD36 pertains to obesity, we compared the body mass index (BMI) of 30 SARIFA-positive and 30 SARIFA-negative patients." (PMID 38216952, 2024). "We observed significant upregulation of proteins like COL1A1, COL6A3, FABP4, and LEP in individuals with obesity, indicating potential roles in adipose tissue dysfunction and metabolic dysregulation." (PMID 38732002, 2024). "The volcano plot also confirmed significant downregulation of various genes in inflammation and obesity including IL-6, IL-1B, CCL2, PPARg, and Fabp4." (PMID 38512816, 2024). "It is also claimed that pharmacological modification of FABP4 function by specific inhibitors would be a novel therapeutic strategy to treat CVD, obesity and atherosclerosis." (PMID 38784129, 2024). "Similar results were found at the follow up visit for a subset (N = 80) of participants, and five proteins were elevated in the obesity group compared to NOH group, four of which (LEP, CSTB, FABP4 and SSCAD) were also identified in the baseline." (PMID 38548792, 2024). "In addition, FABP-4 may affect CRC development through its effects on inflammation and insulin resistance, two pathways that have been demonstrated to play a role in obesity-associated CRC." (PMID 37833736, 2023). "The activated AMPK regulated the mRNA expression related to adipogenesis (PPARγ, C/EBPα, FABP4), lipogenesis (SREBP-1c, ACC, FAS), and lipolysis (ATGL, HSL) to inhibit obesity." (PMID 36678138, 2023). "Indeed, a previous study reported that liver FABP4 mRNA levels are elevated in patients with obesity and insulin resistance as well as in ob/ob mice, suggesting that the liver could also be a source for circulating FABP4 levels in case of obesity." (PMID 35909571, 2022). "Although these data suggest the existence of an endocrine circuit between FABP4 and insulin, which could coordinate the response of β-cells to obesity, there is a lack of further studies confirming the role of this endocrine loop in β-cell compensatory insulin hypersecretion during obesity." (PMID 35628332, 2022). "The link between inflammation and lipid metabolism indicates a key role for fatty acid-binding protein 4 (FABP4; also known as adipocyte protein 2; aP2) in neuroinflammatory diseases such as obesity and Alzheimer’s disease (AD)." (PMID 35457171, 2022). "The obesity- and inflammation-related gene (IL-6, TNF-α, IGF-1, leptin, AP2/FABP4, AMPK-α2, β3AR, and PPAR-γ) expressions in the liver and epididymal adipose tissue were reduced in the PHPB-treated group." (PMID 35386305, 2022). "Among those genes are insulin receptors, fatty acid synthase, lipoprotein lipase, adiponectin, leptin, acetyl-CoA carboxylase beta, and fatty acid binding protein 4 (FABP4), the latter being a new player connecting obesity with breast cancer development." (PMID 33801973, 2021). "The expression of fatty acid binding protein 4 (FABP4) and adiponectin (ADIPOQ) is highly regulated during adipocyte differentiation and negatively correlated with obesity." (PMID 33626085, 2021).